IL6 (interleukin 6)
Diseases named in the same sentence as IL6 in open-access papers (continued):
Sharing a sentence is not in itself a finding about the gene and the disease.
COVID-19 (continued). "Based on this analysis of the primary COVID-19 data, elevated levels of CRP, TNF-α, and IL-6 were found to be associated with increased odds of the severe form of COVID-19 that can result in liver damage in these cases." (PMID 33244370, 2020). "Higher serum levels of pro-inflammatory cytokines, including IL-6, are found in severe cases of COVID-19, and thought to contribute to a fatal outcome." (PMID 32574323, 2020). "Conclusively, increase of serum IL-6 is common in severe and critical forms of COVID-19, especially in critical cases." (PMID 33329518, 2020). "The results of pooled analysis showed that anti-IL-6 signaling agents plus SOC significantly decreased the mortality rate relative to SOC alone in patients with COVID-19 (pooled OR = 0.61, 95% CI 0.45–0.84, p = 0.002)." (PMID 33384605, 2020). "In this review article, it is highlighted the implications of pleiotropic functions of interleukin-6 (IL-6) for one of the therapeutic options targeting for COVID-19." (PMID 33024459, 2020). "In severe cases of COVID-19 with cytokine release, tocilizumab, an IL-6 antagonist, which is humanized IgG1 monoclonal antibody to the IL-6 receptor, has been used as a potential therapy for SARS-CoV-2." (PMID 32450787, 2020). "COVID-19 patients coexisting with diabetes, hypertension, or neoplasia had significantly higher levels of IL-6 and IFN-γ from the early stage of infection—usually accompanied by decreased lymphocytes—and were prone to organ and coagulation disorders." (PMID 33232277, 2020). "We will discuss VTE in COVID-19 patients highlighting the role of D-dimer, fibrinogen, and interleukin-6 (IL-6)." (PMID 33223833, 2020). "There is a growing body of evidence confirming the benefit of targeting the IL-6 pathway in patients with COVID-19, most notably in a recent single-arm study in China with tocilizumab in critically ill COVID-19 patients." (PMID 32423024, 2020). "Except for 1 patient, all other (7/8) patients had IL-6 levels above this value in severe COVID-19, whereas only one person (1/15) with mild infection had IL-6 levels > 7 ng/L." (PMID 33199778, 2020). "This IL-6 overproduction is the justification for using IL-6 receptor antagonists such as tocilizumab in COVID-19 clinical trials." (PMID 32321823, 2020). "Starting from these evidences, IL-6 has been proposed as a promising therapeutic target in COVID-19." (PMID 33634100, 2020). "Flow cytometric analysis of unstimulated whole blood samples revealed a significant increase in the percentage of IL-6+ CD14+ monocytes in patients with severe COVID-19 (n=4) compared with healthy volunteers (n=5)." (PMID 32503877, 2020). "It has been well demonstrated that COVID-19 patients exhibited elevated inflammatory cytokines such as IL-1β, IL-6 and TNF-α in their serum." (PMID 33172355, 2020). "Investigations of different potential therapeutic strategies for COVID-19 cytokine storm syndrome are ongoing that use corticosteroids, IL-6 blockade and IL-1 inhibition." (PMID 32793246, 2020). "An excessive increase of C-reactive protein (CRP), IL-6, and ferritin observed in COVID-19 cases was termed CRS in analogy to similar findings in hemophagocytic lymphohistiocytosis and CAR-T cell therapy." (PMID 33154972, 2020). "Recent studies report that the serum of COVID-19 patients showed elevated cytokine levels (C-reactive protein, IL-6, IL-8, and monocyte chemotactic protein-1), high complement levels (C5a), and reduced lymphocyte counts." (PMID 33537347, 2020). "In hospitalized COVID-19 patients, IL-6 levels increase over time and its blood level is a robust risk factor for adverse outcomes, including in-hospital death." (PMID 32849908, 2020). "Clinical comparison with the overtime variation of IL-6 observed in COVID-19 patients treated with oXiris is particularly interesting." (PMID 33046113, 2020).
COVID-19 (continued). "In moderate COVID-19 cases, bronchoalveolar macrophage-epithelial interactions promote an increase in IL-6 and a decrease in the counts of total T-cells, particularly CD4+ and CD8+ T-cells." (PMID 32517353, 2020). "Based on this evidence, several IL-6 inhibitory agents such as tocilizumab and sarilumab were repurposed in the setting of severe COVID-19." (PMID 33442386, 2020). "Our interpretation of the recently published clinical trials from COVID-19 patients suggests that the clinical efficacy in preventing COVID-19 mortality using IL-1 blockade is subjected to notable caveats, while that for IL-6 blockade is suboptimal." (PMID 32766256, 2020). "We first compared the levels of IFN-γ, TNF-α, IL-2, IL-4, IL-6 and IL-10 in serum samples from control group and COVID-19 patients." (PMID 32475230, 2020). "Aberrant expressions of a variety of cytokines are evident in severely ill COVID-19 patients, while elevated plasma interleukin-6 (IL-6) levels were seen in patients with cardiac injury." (PMID 32645974, 2020). "High mobility group box 1 protein (HMGB1), which activates the inflammasome in the lungs leading to ARDS/ALI, is upstream of IL-6 release, and has been suggested to play a key role in the inflammatory response occurring in the lungs of COVID-19 patients." (PMID 33149733, 2020). "Severe COVID-19 often elicits a strong inflammatory response with elevation in several cytokines, such as IL-6." (PMID 33195334, 2020). "report a significantly higher proportion of inflammatory monocytes with a high expression of IL-6 and granulocyte–macrophage colony-stimulating factor (GM-CSF) in the peripheral blood of COVID-19 patients." (PMID 33584679, 2020). "The potential value of using IL-6 blockade to treat COVID-19 patients was discussed early during the 2020 SARS-CoV-2 outbreak." (PMID 33071786, 2020). "They proposed that tocilizumab, a recombinant humanized monoclonal antibody against the receptor of IL-6, can serve as a potentially effective treatment for cases presenting as severe COVID-19." (PMID 32661796, 2020). "It is now appreciated that COVID-19 afflicted individuals with major respiratory symptoms have pathologically elevated levels of pro-inflammatory cytokines including IL-6, IL-8 and TNF-α." (PMID 32704455, 2020). "In COVID-19, viral load, IL-6, and severity are strongly correlated in adults but surprisingly not in children." (PMID 32903279, 2020). "COVID-19 generates a general increase in inflammatory cytokines, such as IL-1β and IL-6, and a mortality rate of 7.5%." (PMID 32973818, 2020). "In two reports with 15 and 20 patients each, COVID-19 patients treated with anti-IL-6 antibodies had C-reactive protein and lymphocyte levels returning to normal after treatment." (PMID 33324210, 2020). "Higher levels of several inflammatory cytokines including TNF-α, IL-6, and IL-1 and inflammatory chemokines such as CCL2, CCL3, and CXCL10 are associated with disease severity and death in COVID-19 patients." (PMID 33138195, 2020). "The significant increase in the levels of TNF-α and IL-6 in the plasma of patients with COVID-19 is related to many kinds of inflammatory immune cells that secrete inflammatory factors." (PMID 32976531, 2020). "The JAK-dependent pathways are involved in producing a variety of cytokines and increased levels of inflammatory factors including IL-6 and IL-7 that can involve in the pathogenesis of COVID-19." (PMID 32494546, 2020). "Patients with COVID-19 have been found to have high levels of proinflammatory cytokines such as IL-6, IL-1β, IP10, and MCP-1." (PMID 33284413, 2020). "We recently reported that COVID-19 patients had lower concentrations of interleukin (IL)-6 compared to non-COVID-19 patients with severe pneumonia." (PMID 33272291, 2020). "The levels of serum cytokines such as IL-6, IL-10, perforin, granulysin, sFas, and granzyme B in COVID-19 patients were significantly higher than those in healthy controls." (PMID 33154753, 2020).
COVID-19 (continued). "This is in controversy with the high secretion of IL-6 in COVID-19 which is an initiator mechanism for C-reactive protein (CRP) production and cytokine storm." (PMID 32754004, 2020). "The mean IL-6 level before tocilizumab was 102.1±535.1 pg/mL, indicating that IL-6 was upregulated in these COVID-19 patients." (PMID 33031060, 2020). "Follow-up analysis of COVID-19 patients demonstrated that humoral immune responses were positively correlated with the levels of IL-6, C-X-C motif chemokine 10 (CXCL10), and C5a." (PMID 32963357, 2020). "Blocking antibodies or small molecules targeting IL-6 or its signal transduction pathways have been used in the clinical trials to treat COVID-19 patients." (PMID 33488599, 2020). "Severe COVID-19 patients often display a severe pulmonary involvement and develop neutrophilia, lymphopenia, and strikingly elevated levels of IL-6." (PMID 32681497, 2020). "Daclatasvir was also shown to reduce SARS-CoV-2-induced enhancement of TNF-α and IL-6, key contributors to the cytokine storm, observed in some COVID-19 patients." (PMID 33024223, 2020). "Our findings revealed a significantly associated with elevated levels of anti-inflammatory cytokines involving IL-6 and IL-10 among severe and expired patients with COVID-19." (PMID 32822430, 2020). "A retrospective, multicentre study of 150 COVID-19 patients, showed that the patients that died had higher levels of serum ferritin, C-reactive proteins, and IL-6 as compared to the survivors, indicating that hyperinflammation contributed to death." (PMID 32519302, 2020). "Our results showed that, Tregs are significantly decreased in COVID-19 patients, accompanied by increased IL-6." (PMID 33244382, 2020). "Treatment of COVID-19 patients with IL-6 antagonists with tocilizumab and sarilumab also raises safety concerns as these are known to cause endocrinological, hematological, gastrointestinal and cardiovascular adverse effects." (PMID 33708109, 2020). "In a retrospective single-center study involving 94 confirmed COVID-19 patients, therapeutic regimens of IFN-α + LPV/r and IFN-α + LPV/r + RBV were found to be beneficial for reducing IL-6 and C-reactive protein levels in COVID-19 patients." (PMID 34765999, 2020). "Clinical studies have revealed that COVID-19 patients admitted to intensive care have increased expression of inflammatory cytokines (IL-6, IL-10, IL-2, and IFN-γ)." (PMID 33041797, 2020). "While HS-CRP increases in patients with COVID-19, IL-6 promotes the secretion of antibodies by B lymphocytes and, specifically contributes to the function of natural killer lymphocytes." (PMID 33235220, 2020). "Of note, clinical trials to assess cytokine blockade, including canakinumab and tocilizumab (targeting IL-6) in patients with COVID-19 are ongoing." (PMID 33553222, 2020). "These patients show elevated concentrations of IL-6 as a common trait, which is similar to what is seen in adults with COVID-19 who are severely ill." (PMID 32973818, 2020). "Our study revealed that severe COVID-19 patients with comorbidities had higher levels of inflammatory indices, including blood interferon-γ, interleukin (IL)-6 and c-reactive protein levels as well as the erythrocyte sedimentation rate." (PMID 33232277, 2020). "As LMWH inhibits HPSE activity and it is known that HPSE deficiency reduces expression of various cytokines, we analyzed the effect of prophylactic LMWH on HPSE activity, HS levels and IL-6 levels in plasma of COVID-19 patients." (PMID 33123154, 2020). "The induction of IL-6 during severe COVID-19 has led to trials of blocking antibodies to the IL-6 receptor with mixed results." (PMID 32838342, 2020). "This clinical cross-sectional study identified a decrease and increase of mRNA level in the T reg family and IL-6 in COVID-19 patients, respectively." (PMID 33244382, 2020).
COVID-19 (continued). "To investigate the clinical significance of severe IL-6 storms, we analyzed the relationship between maximal plasma IL-6 and the outcomes of COVID-19 patients." (PMID 32917983, 2020). "Recent findings state that IL-6 level is high in severe COVID-19 patients, remaining low in mild cases, and negatively correlates with NK cell count and activity." (PMID 33382687, 2020). "Use of low molecular weight heparin is reported to be associated with improvement in aberrant coagulation and a reduction of IL-6 levels, and is reported to increase survival in COVID-19." (PMID 32848776, 2020). "Multiple studies show that elevated expression of IL-6 can be used to predict the severity of COVID-19, with increased need for ICU care and progression to ARDS." (PMID 32992775, 2020). "Increase in mortality in those with COVID-19 is due to acute respiratory distress syndrome (ARDS) due to unantagonized production of pro-inflammatory cytokines IL-6 and TNF-α." (PMID 33390994, 2020). "A case report demonstrated the potential for tocilizumab therapy in treating severe COVID-19 illness, where a single dose on day 24 of symptoms led to progressive reduction in IL-6 levels and resolution of symptoms." (PMID 32655581, 2020). "Collectively, these results indicate a coordinate adaptive immune response to SARS-CoV-2, enhanced by basophils and possibly suppressed by hyperinflammatory cytokine responses with high IL-6 levels during acute COVID-19." (PMID 32838342, 2020). "Laboratory analysis aiming to distinguish severe from mild disease suggested that circulatory inflammatory markers including interleukin (IL)-6, ferritin, and D-Dimer were closely related to severe COVID-19 in adults." (PMID 32517353, 2020). "Most patients with COVID-19 exhibit substantially elevated serum levels of pro-inflammatory cytokines, including IL-6, IL-2R, IL-8, IL-10 and TNFα, which is characterized as cytokine storms." (PMID 33365277, 2020). "Of note, the IL-6 levels described in COVID-19 patients are a log-fold lower than those described in classic cytokine storm." (PMID 33123165, 2020). "A recent study suggested that IL-6 is one of the cytokines responsible for immune dysregulation or macrophage activation syndrome in severe COVID-19 patients, and the use of Tocilizumab partially rescued SARS-CoV-2 associated immune dysregulation." (PMID 33284859, 2020). "Elevated levels of IL-6 in patient plasma have been correlated to respiratory failure in COVID-19 patients." (PMID 32591408, 2020). "The expression level of IL-6 represented almost 18-fold increase in COVID-19 patients compared to healthy controls." (PMID 33244382, 2020). "Studies of COVID-19 patients' serum show lymphopenia and a marked increase in inflammatory markers such as interleukin-6 (IL-6) and C-reactive protein (CRP)." (PMID 33195363, 2020). "IL-6 concentrations are increased 2.9-fold in patients with complicated COVID-19 vs. uncomplicated, and IL-6 levels are predictive of respiratory failure." (PMID 32848776, 2020). "For instance, IL-6 and TNFα released by COVID-19 are also triggered by malaria and obesity as far as inflammation-induced insulin resistance is concerned." (PMID 33134395, 2020). "These activated T cells together with inflammatory monocytes (CD14+CD16+ and high expression of IL-6) contribute to severe pulmonary syndrome in COVID-19 patients." (PMID 33302366, 2020). "Specifically, weplan to study Clinical samples from COVID-19 patients with comorbidities for the presence of rs2910164 GC and effect on IL-6 level." (PMID 33072191, 2020). "COVID-19 patients have high levels of circulating interleukin 2 receptor (IL-2R), IL-6, IL-10 and tumor necrosis factor α (TNFα)." (PMID 33365277, 2020). "Based on emerging information treating SARS-CoV- 2-infected patients, modulating or inhibiting the IL-6 signaling pathway to mitigate the inflammatory response related to COVID-19 is an attractive idea." (PMID 33292350, 2020).
COVID-19 (continued). "Consistent with a previous literature, the IL-6 increase in COVID-19 severe patients should be related to HMGB1 macrophage release, but further investigations are needed." (PMID 32724296, 2020). "STAT3, which is critical for IL-6 signaling, was also expressed significantly less in patients with COVID-19 compared to patients with influenza despite the elevated levels of IL-6 circulating in these subjects." (PMID 33187979, 2020). "COVID-19 severity is associated with increased proinflammatory cytokines and chemokines and IL-6, specifically, is predictive of COVID-19 fatality." (PMID 32655582, 2020). "As a promising therapeutic target of severe COVID-19, IL-6 was downregulated by XBJ in clinical studies and pre-clinical studies." (PMID 33986658, 2020). "Despite the fact that immunosuppressive-drugs are generally not recommended during viral infections, tocilizumab has been tested in COVID-19 patients with elevated IL-6 levels, and exhibited several beneficial effects." (PMID 33102489, 2020). "In resting conditions, only IL-1β, IL-6, and IL-10 were detected in supernatants and showed similar levels between COVID-19 patients and healthy controls." (PMID 33634100, 2020). "Severe COVID-19 involves pneumonia and fatal outcomes that often correlate with elevated plasma levels of interleukin-6 (IL-6) and the cytokine storm." (PMID 33339432, 2020). "It is an IL-6 receptor (IL-6R) blocker that can effectively block the IL-6 signal transduction pathway and thus is likely to become an effective drug for patients with severe COVID-19 and to reduce the mortality." (PMID 32806657, 2020). "This drug can also reduce the expression of TNF α and IL-6, which are responsible for COVID-19 pathogenesis." (PMID 33178016, 2020). "Other studies have observed the presence of elevated levels of IL-6 and other proinflammatory cytokines in patients with severe COVID-19." (PMID 32967329, 2020). "Hierarchical clustering analysis show links between COVID-19, IL-6 levels, and amino acid metabolism, purines, acylcarnitines and fatty acids." (PMID 33495710, 2020). "The excessive host immune responses mediated by pathogenic T-cells and inflammatory CD14+ CD16+ monocytes that express high levels of IL-6 in blood samples of COVID-19-S patients were also observed in a recent study." (PMID 34676126, 2020). "Virus-infected cells lead to cytokine storm and this is observed as an increase in IL-6 levels in COVID-19." (PMID 33148349, 2020). "The level of IL-6 is markedly increased in COVID-19 patients with acute respiratory distress syndrome (ARDS)." (PMID 32685301, 2020). "IL-6 and IL-10 were detected in supernatants from resting PBMCs from COVID-19 patients and were increased 225- and 6-fold, respectively, after co-culture (p = 0.0039 by Wilcoxon-matched pairs test)." (PMID 33634100, 2020). "Inflammatory cytokines IL1β, IL6, IL8, and TNFα associated with cytokine storm were significantly increased in the plasma of moderate and severe COVID-19 patients (p < 0.0001 for all cytokines)." (PMID 33585507, 2020). "Specifically, in the blood of COVID-19-infected patients, IL-6, IFNγ, MCP1, and IP-10 were found elevated." (PMID 33352869, 2020). "The recent promising outcome of anti-IL-6 monoclonal antibodies therapy in COVID-19 patients supports the conclusion of this study that Notch-1/IL-6 signaling is key to understand and treat inflammation." (PMID 33072191, 2020). "Anemic patients had increased levels of inflammation markers such as interleukin-6 and C-reactive protein and survived a more severe course of COVID-19." (PMID 33087116, 2020). "This is consistent with clinical manifestations including observations of high IL6 levels in COVID-19 patients." (PMID 33293514, 2020). "Excessive accumulation of inflammatory cytokines (IL-1β, TNF, IL-6, etc.), which are produced mainly by monocytes and macrophages, is characteristic of the severe course of COVID-19." (PMID 33329059, 2020).